KRAS (KRas proto-oncogene, GTPase)
Diseases named in the same sentence as KRAS in open-access papers (continued):
Sharing a sentence is not in itself a finding about the gene and the disease.
tumor (continued). "ABab-I mice mount robust CD8+ T cell responses in vivo against viral (Cytomegalovirus (CMV), Human Papillomavirus (HPV)), tumor-associated antigens (MAGE-A12), and tumor-specific neoantigens (mutant KRAS and CALR)." (PMID 40593800, 2025). "Nevertheless, the efficacy of direct targeting of KRAS mutations to inhibit tumor development remains doubtful." (PMID 39810420, 2025). "TSAs, in contrast, are exclusively present on tumor cells, with examples such as mutated KRAS (mKRAS)." (PMID 40723238, 2025). "The majority of KRAS G12C mutations result from smoking and are correlated with an elevated tumor mutational burden, which is indicative of the potential response to immune checkpoint inhibitors." (PMID 40136368, 2025). "Preclinical studies have shown that WEE1 inhibitors, either as monotherapies or in combination with targeted agents, are effective across various tumor types harboring KRAS mutation." (PMID 40885709, 2025). "These radiomic features provide complete tumour information that cannot be obtained via quantitative visualization and are highly important for identifying the KRAS mutation status." (PMID 40421293, 2025). "Overall, KRAS co-mutations regulate the tumor immune microenvironment through distinct mechanisms, underscoring the necessity of optimizing personalized therapeutic strategies and validating their potential through preclinical studies." (PMID 40303413, 2025). "Here, we have successfully designed mutant-specific ASOs for selectively silencing mutations in the KRAS gene in various tumor cell types, while minimizing the cross-reaction with wild-type genes." (PMID 40585984, 2025). "Pro-angiogenic factors like VEGF-A and oncogenic drivers such as mutated KRAS within TDEs further stimulate vascular proliferation and remodeling, supporting tumor expansion and survival." (PMID 40149276, 2025). "In experimental cancer models, multiple mutant KRAS variants led to increased IL-8, which promoted tumor-associated inflammation, angiogenesis, and tumor growth." (PMID 40165901, 2025). "Another significant factor was the presence of a KRAS mutation, known to drive tumor aggressiveness, resistance to targeted therapies, and increased metastatic potential." (PMID 39926284, 2025). "In all TCGA cohorts, exploratory analysis of the DNA‐Seq somatic mutation distribution for KRAS according to tumor type confirmed the occurrence of this mutation in the literature." (PMID 40013338, 2025). "Our results demonstrate that the HiFiCas9-mediated KRAS targeting system can selectively eliminate tumor cells by targeting KRASG12C and KRASG12D driver mutations, highlighting its therapeutic potential in preclinical models." (PMID 40890128, 2025). "Comparison of patient-matched fresh plasma and available tumour samples showed identical hotspot mutation in 29 (97%) of 30 patients for KRAS." (PMID 40211189, 2025). "In summary, KRAS mutations reprogram metabolism to suppress immunity and promote tumor immune escape." (PMID 40303413, 2025). "Serial analysis of circulating tumor DNA revealed a reduction in the frequency of KRAS G12C mutations in patients with partial responses, and genomic alterations associated with resistance to divarasib were also identified." (PMID 40940900, 2025). "KRAS mutations have been associated with adenocarcinoma histology, smoking history, higher tumor mutation burden (TMB) and programmed cell death ligand 1 (PD-L1) expression." (PMID 40558308, 2025).
tumor (continued). "This study investigated the molecular heterogeneity and mutational landscape of MCN in relation to PDAC, highlighting the significance of KRAS mutations in tumor progression." (PMID 39906959, 2025). "Emerging molecular markers—such as KRAS mutation status and circulating tumor DNA—offer promising avenues for patient stratification." (PMID 40572765, 2025). "The preclinical evaluation of avutometinib in combination with panitumumab showed significant antitumor activity in CRC PDX models harboring KRAS mutations, with more tumor regression observed in a KRAS G12V PDX model than in a KRAS G12D model." (PMID 40361439, 2025). "Our results highlight the biological complexity of SMARCA4 class 1 versus class 2 mutations and their role in tumor progression when co-mutated with KRAS in patients with NSCLC." (PMID 41007704, 2025). "This study develops a dimeric T cell receptor engager protein specific for tumor KRAS‐G12V mutation." (PMID 40470869, 2025). "By combining KRAS mutation data with clinical factors like tumor size and a blood marker, they developed a scoring system to predict patient outcomes." (PMID 39779977, 2025). "Genetic analysis using Luminex 100/200 technology (Luminex Corporation, Austin, TX, USA) on a formalin-fixed, paraffin-embedded tumor sample from the surgical specimen revealed a KRAS mutation (p.G12V)." (PMID 40134936, 2025). "This leads to a starker separation between EGFR-mutant and KRAS-mutant tumours, while also highlighting the association of other events such as STK11 mutation in the determination of which evolutionary trajectory a tumour will follow." (PMID 41509216, 2025). "A comprehensive analysis involving 47 cell lines underscored the significant impact of tumor cell type on DNA methylation profiling, overshadowing the influence of KRAS driver mutations." (PMID 40981070, 2025). "Unfortunately, the clinical utility of KRAS G12C inhibitors in oral OSCC remains limited due to the very low frequency of KRAS G12C mutations in this tumor type." (PMID 40427514, 2025). "KRAS mutations were more frequently detected in the right-sided tumor than left-sided tumor (P = 0.026)." (PMID 40279317, 2025). "Differential gene expression (DGE) analysis showed up-regulation of several pathways associated with tumor maintenance and progression, such as oxidative phosphorylation, DNA repair mechanisms, inflammation and immune response, and KRAS signaling." (PMID 40523964, 2025). "Consistently, Tumor Mutational Burden (TMB) analysis showed KRAS mutations were higher in tumors with high ALDH3A1 and ALDH3B1 expression (76% and 81%, respectively) than in those with low expression (44% and 38%, respectively)." (PMID 40868269, 2025). "This variability supports both tumor-specific and tumor-agnostic development and provides the rationale for pursuing allele-specific as well as pan-KRAS therapeutic strategies." (PMID 41170373, 2025). "In other types of cancer that include colorectal, lung, and leukemia, KRAS allelic imbalances are also linked to tumor initiation, cell proliferation, invasion, and metastasis." (PMID 40227826, 2025). "They found that higher KRAS mutation levels were linked to faster tumor growth and earlier recurrence after surgery." (PMID 39779977, 2025). "EGFR and KRAS mutations in tumor cells can modulate the function of TILs through complex signaling networks, including secretion of chemokines and cytokines present in the TME/TIME." (PMID 40524071, 2025). "The pattern of KRAS and BRAF mutations across different tumor sites (colon vs. rectum) was significantly associated with KRAS mutation (p=0.03)." (PMID 40949797, 2025). "The relationship between various KRAS mutation sites and neutrophil pro- or anti-tumor phenotypes in different tumor types is somewhat understood." (PMID 40611261, 2025). "KRAS mutations result in the accumulation of lactate and ammonia, and depletion of glutamine in the tumor microenvironment." (PMID 40485603, 2025).
tumor (continued). "KRAS dampens the antitumor activity of tumor-associated macrophages (TAMs) by eliciting the production of various immunosuppressive molecules, inflammatory factors, chemokines, and signaling pathways." (PMID 41184283, 2025). "KRAS mutations dynamically remodel the tumor microenvironment (TME), fostering immunosuppression, metabolic symbiosis, and stromal plasticity." (PMID 40485603, 2025). "Among them, two patients with iCCAs harboring the G12D mutation in KRAS developed the fastest onset of tumor metastasis following surgery, with a progression-free survival period of only 4 months for patient S428 and 7 months for patient S430." (PMID 41301905, 2025). "According to the Catalogue of Somatic Mutations in Cancer (COSMIC), which provides access to comprehensive human tumor mutation databases, KRAS mutations were expressed in about 22% of analyzed tumors, versus 8% for NRAS and 3% for HRAS." (PMID 40002297, 2025). "The efficacy of KRAS-targeted therapies varies considerably by tumor type, reflecting differences in co-mutation landscapes, signaling dependencies, and tumor biology." (PMID 41170373, 2025). "In contrast to primary tumor analysis, the detection of KRAS mutations in cfDNA was markedly lower in our study." (PMID 40943438, 2025). "In the liver orthotopic xenotransplantation assay, simultaneous knockdown of KRAS significantly reduced the stronger fluorescence intensity and larger tumor volume caused by FHL3 than did FHL3 overexpression alone." (PMID 41184244, 2025). "Supporting this evidence, we observed that DUSP6 was significantly upregulated in tumor cell lines harboring a KRAS mutation compared to tumor cells driven by other mutations in the CCLE dataset." (PMID 41028058, 2025). "This variability complicates the development of inhibitors that can effectively target multiple KRAS variants across diverse tumor types." (PMID 40002297, 2025). "Given both KPL and LLC cells are driven by KRAS mutations, it is possible that the observed effects on anti-tumor immunity are specific to tumors with a KRAS mutant background." (PMID 40867322, 2025). "After examining the mechanisms of resistance to KRAS G12C inhibitors, it becomes essential to investigate how KRAS mutations influence the tumor immune microenvironment (TME)." (PMID 40303413, 2025). "KRAS mutations, which are present in approximately 90% of PC cases, drive tumor progression through constitutive MAPK/ERK and PI3K/AKT signaling, influencing the TME and promoting tumor stemness 33,34." (PMID 40740231, 2025). "Using castPCR analysis of tumor DNA samples, the KRAS p.G12D mutation was most frequently identified (48.0% of patients) with a median %mutation of 7.0% (IQR 5.3–13.7%)." (PMID 40943438, 2025). "Another signaling pathway that has been evaluated is KRAS, a proto-oncogene that encodes a small GTPase involved in cell signaling pathways that regulate tumor growth, differentiation, and survival." (PMID 40507337, 2025). "Currently, tumor histopathological examination remains the gold standard for detecting KRAS mutations." (PMID 40653800, 2025). "Although EGFR and KRAS are closely linked within their signaling pathways, harboring oncogenic mutations in these genes differently affects prognosis, tumor biology, histological differentiation and immunogenicity." (PMID 40809430, 2025). "Another rationale for the relevance of the KRAS mutation dose and tumor purity is that KRASG12mut regulates cell proliferation by activating the RAS signaling pathway." (PMID 39779977, 2025). "The whole-exome sequencing revealed a variety of common oncogenic mutations in the original tumor and HMucBOT-2, including KRAS, ARID1A, ARID1B, and NF1, while CDKN2A remained wild-type." (PMID 40427213, 2025). "Longitudinal examination of KRAS mutated ctDNA, as a proxy for tumor burden and chemotherapy resistance, has been compared to the clinically established serum marker carbohydrate antigen 19 − 9 (CA19-9) and imaging data, with promising results." (PMID 41044171, 2025).
tumor (continued). "Recent studies have demonstrated that exosomes carrying KRAS mutations play a pivotal role in promoting tumour progression by facilitating neutrophil aggregation and the formation of neutrophil extracellular traps (NETs)." (PMID 40740862, 2025). "We detected a single KRAS mutation (KRAS p.G12D) in 48% and 75.5% of primary tumor samples with castPCR and dPCR, respectively." (PMID 40943438, 2025). "Combination treatment with oHSV and Trametinib enhanced virus replication mediated by down-regulation of STAT1 and PKR expression or phosphorylation in BRAF V600E-mutated tumor cells as well as BRAF wt/KRAS-mutated tumor cells." (PMID 40248194, 2025). "KRAS mutations showed a strong correlation with advanced tumor stages (p=0.04), particularly in stage IV tumors." (PMID 40949797, 2025). "Experiments in Drosophila and mouse models report that oncogenic RAS/KRAS mutations alone are only sufficient to initiate benign tumours." (PMID 41188521, 2025). "This summary highlights the strong regulatory effect of KRAS mutations on T cells, the anti-tumor workhorses in the immune microenvironment." (PMID 40611261, 2025). "The anticipated enrichment of KRAS WT amplifications in gastroesophageal cancers prompted an in-depth analysis of the co-mutation landscape for this tumor type." (PMID 39711431, 2025). "AI-HOPE-PM utilized the COAD dataset enriched with SDOH and genomic annotations to assess the intersection of insurance status, tumor stage, and KRAS mutation status." (PMID 41342165, 2025). "Molecular analysis of this tumor revealed an activating KRAS mutation as the oncogenic driver mutation for this tumor." (PMID 40012695, 2025). "This formulation enhances lymph node delivery, induces T-cell recognition of KRAS mutations, promotes clearance of KRAS-mutated cancer cells, and lowers the risk of tumor recurrence." (PMID 41320679, 2025). "Loss of RASON impairs tumor growth in vivo and sensitizes KRAS-mutant pancreatic cancer cells to EGFR inhibition, highlighting its function as a key modulator of oncogenic signaling." (PMID 40558487, 2025). "Our results demonstrate the relationship between KRAS mutation and clinicopathological features, with possible impact in clinical tumour stratification and therapeutic management." (PMID 39996841, 2025). "A Kirsten Rat Sarcoma Viral Oncogene Homolog (KRAS) exon 2 c.38G>A (p.G13D) mutation was detected in the tumor tissue, whereas mutations in the epidermal growth factor receptor (EGFR) and anaplastic lymphoma kinase (ALK) were negative." (PMID 40630489, 2025). "The results showed that Case 1 exhibited multiple gene mutations, including FBXW7 and KRAS, with a tumor mutational burden (TMB) of 17.65 muts/Mb before treatment." (PMID 41353695, 2025). "Equally important, additional evidence has validated the function of wild-type KRAS as a tumor suppressor, antagonizing the mutant allele in KRAS dimerization and other biochemical properties." (PMID 40227826, 2025). "The activation of bypass pathways, including HER2 amplification, MET amplification, and PIK3CA/KRAS mutations, promotes tumor survival and proliferation." (PMID 40733125, 2025). "Our data demonstrated that the combination of KRAS ASO with RIG-I agonist significantly induced cell death across all tested KRAS-mutated tumor cell types in vitro." (PMID 40585984, 2025). "KRAS driver mutations have been implicated in modulating the tumor epigenome, particularly by inducing focal changes in DNA methylation patterns rather than widespread global alterations." (PMID 40981070, 2025). "This review outlines the current understanding of how EGFR, KRAS, and other key mutations influence immunotherapy responses and tumor immunology." (PMID 40524071, 2025).
tumor (continued). "KRAS mutations increase Gln uptake and utilization, supporting tumor cell proliferation and survival." (PMID 40641572, 2025). "Beyond its role in tumor progression, YAP/TEAD-mediated signaling has recently been associated with resistance to targeted therapies in other tumor entities, such as KRAS- or EGFR-mutated cancers." (PMID 40649713, 2025). "Key driver mutations, such as EGFR and KRAS, are generally clonal and emerge early in tumor evolution, being present in both primary and metastatic sites." (PMID 41158851, 2025). "The comparative analysis showed a statistically significant association between the number of tumour clusters and KRAS mutation (p = 0.007) in our study group." (PMID 39996841, 2025). "Among the included patients, 45 patients (45%) had a KRAS mutation and 19 patients (19%) a right sided primary tumour." (PMID 41406506, 2025). "The preoperative tumor size and CA 19-9 level were similar to those of the KRAS G12 mutation dosage for OS prediction." (PMID 39779977, 2025). "This suggests that, beyond the well-known STK11/KEAP1, alterations in other tumor suppressors like SMARCA4 (which often co-mutates with KRAS in smokers) and cell cycle regulators (CDKN2A loss) can also diminish the efficacy of KRAS inhibitors." (PMID 40723270, 2025). "In general, these carcinogens induce mutations in KRAS and recapitulate the early stages of tumor development." (PMID 40805126, 2025). "As per the devised categorical rating system, patients were given 1 point each for maximal tumor diameter at baseline CT > 20 mm, preoperative CA 19-9 levels > 150 U/mL, and KRAS G12 mutation dosage based on TS data > 0.195." (PMID 39779977, 2025). "The induction of CD3+ T-cell apoptosis by KRAS mutations not only leads to T-cell depletion and energy starvation but also undermines tumor immune surveillance, ultimately facilitating immune evasion by NSCLC cells." (PMID 40303413, 2025). "In this study, we selected the A549 and H358 cell lines, both of which harbour distinct KRAS mutations (G12S and G12C, respectively), to evaluate Brazilin's efficacy against KRAS‐driven tumours." (PMID 40596709, 2025). "Among the genomic characteristics of NSCLC, the Kirsten rat sarcoma viral oncogene homolog (KRAS) mutation is one of the main tumor drivers, accounting for approximately 25% of all NSCLC cases." (PMID 40506488, 2025). "By cross-talking with cancer-associated fibroblasts, KRAS-mutant tumor cells promote extracellular matrix remodeling (collagen, hyaluronic acid), which enhances tumor growth and invasion." (PMID 41514544, 2025). "This variability highlights the complexity of KRAS mutations and their differential impact on tumor biology." (PMID 40611261, 2025). "CXCL8 (IL-8), a direct transcriptional target of KRAS, is strongly associated with tumor-associated inflammation and angiogenesis." (PMID 40303413, 2025). "KRAS mutation increase glycolysis metabolism, oxidative phosphorylation, and hypoxia pathway activation, promoting tumor development and restricting CD8+PD-1−T infiltration, thereby suppressing the anti-tumor immune response." (PMID 41184283, 2025). "The same team claimed that KRAS mutations indicate a more aggressive tumour behaviour with higher recurrence and worse disease-specific survival." (PMID 39941911, 2025). "Emerging evidence suggests that somatic mutations in driver genes can modulate tumor immunogenicity; for example, ALK rearrangements, EGFR mutations, and KRAS mutations correlate with immunosuppressive tumor microenvironments (TMEs)." (PMID 40873541, 2025). "MSI-CRC tumours frequently harbour mutations in tumour suppressor genes such as KRAS and pro-oncogenic genes, including BRAF; the V600E mutation in BRAF in particular is characteristic of sporadic MSI-CRC." (PMID 40647444, 2025).